GABPA (GA binding protein transcription factor subunit alpha)
Description:
Transcription factor capable of interacting with purine rich repeats (GA repeats). Positively regulates transcription of transcriptional repressor RHIT/ZNF205. (Microbial infection) Necessary for the expression of the Adenovirus E4 gene.
Synonyms: E4TF1A; NFT2; NRF2; E4TF1-60; NRF2A; RCH04A07
Tractability: PROTAC: ubiquitination databases record sites on it; its protein half-life has been measured.
Gene: Protein-coding gene on chromosome 21 (25,734,570 to 25,772,460, forward strand). Ensembl gene ENSG00000154727.
Subcellular location: Nucleus
Subcellular location (Human Protein Atlas): Nucleoplasm
Pathways (Reactome):
Organelle biogenesis and maintenance: Transcriptional activation of mitochondrial biogenesis
Gene Ontology:
Molecular function: DNA-binding transcription activator activity, RNA polymerase II-specific; protein binding; RNA polymerase II cis-regulatory region sequence-specific DNA binding; sequence-specific double-stranded DNA binding; transcription cis-regulatory region binding; DNA-binding transcription factor activity; DNA-binding transcription factor activity, RNA polymerase II-specific; chromatin binding; sequence-specific DNA binding
Biological process: positive regulation of transcription by RNA polymerase II; cell differentiation; regulation of transcription by RNA polymerase II; ERBB signaling pathway; neuromuscular junction development; regulation of DNA-templated transcription
Cellular component: chromatin; nucleoplasm; nucleus
Genetic constraint (gnomAD): Loss-of-function variants: 0 observed, 35.94 expected, observed/expected ratio (o/e) 0, 90% interval 0 to 0.083. The upper end of that interval is the gene's LOEUF score, 0.083, which puts it in group 1 of 6, group 1 being the genes least tolerant of losing a copy. Missense variants: 138 observed, 348.14 expected, observed/expected ratio (o/e) 0.4, 90% interval 0.34 to 0.46. Synonymous variants: 117 observed, 117.53 expected, observed/expected ratio (o/e) 1, 90% interval 0.86 to 1.16.
Homologues: Orthologues: chimpanzee GABPA (100% identical), macaque GABPA (99% identical), dog GABPA (99% identical), guinea pig GABPA (98% identical), rat Gabpa (98% identical), mouse Gabpa (96% identical), rabbit GABPA (94% identical), pig GABPA (93% identical), tropical clawed frog gabpa (77% identical), zebrafish gabpa (74% identical), Drosophila melanogaster Ets97D (38% identical). Paralogues in human: FLI1 (27% identical), ETS2 (27% identical), ERG (27% identical), ETS1 (26% identical), ETV1 (19% identical), ETV5 (19% identical), ETV4 (17% identical), SPDEF (17% identical), ELF4 (17% identical), ETV2 (16% identical), ELF2 (16% identical), ELK3 (16% identical), and 16 more.
Diseases named in the same sentence as GABPA in open-access papers:
GABPA is named in the same sentence as 42 diseases in open-access papers, as found by Europe PMC text mining. Sharing a sentence is not in itself a finding about the gene and the disease. The quoted sentences say what the papers report.
glioblastoma (13 papers, 2019 to 2025). The most malignant astrocytic tumor (WHO grade IV). "Recent studies showed that the GABP tetramer forming isoforms, especially GABPB1-L, activate the mutant TERT promoter and a disruption of B1L generates telomeric loss in glioblastoma cell lines introducing the importance of GABPA/B isoforms in the mutated TERT promoter dependent gliomas." (PMID 34194624, 2021). "GABPA was associated with multiple cancers and specifically with glioblastoma." (PMID 33647036, 2021). "In contrast, restoration of the promoter mutation to the wild-type sequence or depletion of GABPA in melanoma and glioblastoma cell lines enables silencing of the histone mark, suggesting that GABPA binding to TERT promoter is a key step to change the chromatin status." (PMID 30709063, 2019). "These mutations induce expression of the TERT oncogene by creating a GABPA transcription factor binding site in glioblastoma and melanoma." (PMID 40359938, 2025). "Overall, GABPA seems a solid candidate to explore TPM-specific epigenetic blockade of TERT re-expression in glioblastoma, but its role in thyroid cancers remains uncertain." (PMID 35053525, 2022). "They subsequently showed that GABPA is also able to upregulate mutant TERT in glioblastoma and melanoma cells, but it does so, at least partially, via long-range chromatin interactions." (PMID 35053525, 2022). "GABPA has long been shown to play oncogenic roles in the pathogenesis of leukemia, prostate cancer, glioblastoma and other malignancies." (PMID 35549739, 2022). "In contrast, continued GABPA knockdown in U251 glioblastoma cells confirmed the previously shown significant reduction in TERT expression." (PMID 35053525, 2022). "Several studies, typically using siRNA silencing, reporter assays, and ChIP approaches, on glioblastoma cells carrying TPMs demonstrated that the ETS factor GABPA controls TERT mutant promoter expression." (PMID 35053525, 2022). "Bell and colleagues sequentially knocked-down thirteen ETS transcription factors in two glioblastoma lines and showed that GABPA selectively reduces TERT transcription in the presence of the c.-124C > T mutation." (PMID 35053525, 2022). "TERT promoter mutations occur in the majority of glioblastoma, bladder cancer (BC), and other malignancies while the ETS family transcription factors GABPA and its partner GABPB1 activate the mutant TERT promoter and telomerase in these tumors." (PMID 31802036, 2020). "Previous studies in BRAF wild-type glioblastoma models have already demonstrated a central role of GABPA in activation of the mutant TERT promoter." (PMID 31391125, 2019). "Several studies in TERT-mutant glioblastomas demonstrated that GABPA, an ETS factor acting as a tetrameric protein along with its GABPB isoform, drives TERT-mutant transcription in this tumor lineage, opening the door to targeting the GABPA/GABPB axis to achieve TERT downregulation in that context." (PMID 35053525, 2022). "Indeed, glioblastoma cells knocked-out of GABPB1, the GABPA partner required for activation of the mutated TERT promoter, was shown to undergo telomere shortening, senescence or apoptosis and eventual loss of tumorigenesis." (PMID 35549739, 2022). "This same group elegantly showed that GABPA acts as a tetramer with their beta-isoform (GABPB) and that GABPβ1L disruption reverses replicative immortality in glioblastoma cells with TPMs." (PMID 35053525, 2022). "GABPA depletion or the disruption of the GABPA/GABPB1 complex by knocking down GABPB1 was shown to inhibit telomerase, thereby eliminating the tumorigenic potential of glioblastoma cells." (PMID 31802036, 2020). "In particular, the GABPA/B tetramer selectively binds and activates the mutant TERT promoter, thus inducing overexpression of the TERT gene in several tumour types, including glioblastoma, melanoma, hepatocellular carcinoma and bladder cancer." (PMID 38033865, 2023).
glioblastoma (continued). "GABPA is central to TERT expression in glioblastoma as it had been shown that the knockdown of GABPA significantly reduced mutant promoter activity without affecting wild-type promoter activity." (PMID 33547950, 2021). "We found positive correlated relationship between GABPA and GABPB1 (r = 0.6, 95% CI = 0.06–0.91; p = 0.035), GABPB1-L (r = 0, 8, 95% CI = 0.56–0.97; p = 0.0008) and GABPB1-S (r = 0.6, 95% CI = 0.02–0.9; p = 0.045) in primary glioblastomas." (PMID 34194624, 2021). "GABPA and GABPB1, GABPB1-L and GABPB1-S positive correlate in primary glioblastomas." (PMID 34194624, 2021). "Consequently, in this study we investigated the mRNA expression level of TERT and all GABPA/B isoforms and their correlation and interplay in the grade II, grade III gliomas as well as in the primary and secondary glioblastomas to understand their role in the gliomagenesis." (PMID 34194624, 2021). "We observed that, unlike in other TPM-carrying cancers such as glioblastomas, ETS factor GABPA does not unambiguously regulate transcription from the TERT mutant promoter in thyroid specimens." (PMID 35053525, 2022). "Furthermore, the tetrameric complex GABPA/GABPB plays an important role in the regulation of TERT transcription since it selectively binds and activates the mutant but not the wild-type TERT promoter in glioblastoma." (PMID 38033865, 2023).
bladder cancer (9 papers, 2020 to 2025). "In bladder cancer, GABPA is involved in the recruitment of two transcriptional co-regulators of telomerase expression, namely, TRIM28 (tripartite motif containing 28) and TRIM24, to the mutant TERT promoter −124A." (PMID 38033865, 2023). "In bladder cancer, GABPA activates the Fox1A and GATA3 genes, thereby promoting cancer cell differentiation." (PMID 35549739, 2022). "Several studies have revealed that the abnormal expression of GABPA was related to poor survival in various cancers, including leukemia, hepatocellular carcinoma, thyroid cancer, bladder cancer, and prostate cancer." (PMID 34306255, 2021). "Our study agrees with several recent investigations, which showed that the lower GABPA expression is correlated with bigger tumor sizes, advanced stages or grades, local and distant metastasis, and poor outcomes in patients with thyroid carcinoma, hepatocellular carcinoma, or bladder cancer." (PMID 34306255, 2021). "In bladder cancer (BC) cells, GABPA similarly inhibited Col I and III formation, whereas Col levels increased upon GABPA depletion, revealing its modulation of extracellular matrix (ECM) deposition and stiffness." (PMID 40813762, 2025). "Moreover, GABPA regulates the expression of CDKN1A and serves as a tumor suppressor in bladder cancer." (PMID 34338139, 2021).
breast carcinoma (9 papers, 2014 to 2024). "In particular, CpGs located in the DDX43 gene, which are involved in spermatogenesis and male fertility, or CpG located in the GABPA gene, are associated with early onset Alzheimer’s disease, Parkinson’s disease, and breast cancer." (PMID 38053163, 2023). "This is further supported by the fact that GABPA has also been heavily associated with early onset of Alzheimer's disease, Parkinson's disease, breast cancer and autism." (PMID 35568878, 2022). "In human breast cancer cells, miR-378 induces metabolic shift by inhibiting the expression of two PGC1β partners, ERRγ and GABPA." (PMID 26898952, 2016). "Through downregulation of GABPA and ERRγ, two PGC-1β partners, miR–378a–5p helps to orchestrate the Warburg effect in breast cancer cells." (PMID 24651706, 2014). "Promoter binding was also absent in MCF-7 and MDA-MB-231 cells, indicating that GABPA may upregulate Nm23-H1 protein expression through other non-transcriptional mechanisms in breast cancer cells." (PMID 33436746, 2021). "In breast cancer cells, a high level of miR-378* induces the metabolic shift from an oxidative to a glycolytic bioenergetics pathway by inhibiting the expression of two PGC-1β partners, ERRγ (estrogen-related receptor gamma) and GABPA (GA binding protein transcription factor, alpha subunit)." (PMID 29445084, 2018).
thyroid cancer (9 papers, 2019 to 2025). "In FTC cell lines, we observed reduced expression levels of the thyroid-cancer associated miRNA miR-34a-5p upon DICER1 or GABPA depletion, suggesting that components of the miRNA machinery are affected by the general DICER1 down-regulation seen in FTCs." (PMID 32163919, 2020). "We have recently identified that DICER1, an endoribonuclease responsible for miRNA maturation, is the GABPA target gene in thyroid cancer (TC) cells, and many miRNAs were positively correlated with GABPA expression in primary TC tumors." (PMID 40813762, 2025). "In recent studies, we and others identified that DICER1 was the direct target gene of GABPA in thyroid carcinoma cells, and many miRNAs were positively correlated with GABPA expression." (PMID 40813762, 2025). "For instance, DICER1, a ribonuclease functioning in the microRNA (miRNA) processing machinery, is transcriptionally activated by GABPA through which the invasive phenotype and metastasis of thyroid cancer are inhibited." (PMID 35549739, 2022). "In this regard, the capacity of GABPA to bind to mutant TERT promoters in thyroid cancer was reported through ChIP assays on the K1 papillary thyroid carcinoma cell line." (PMID 35053525, 2022). "Conversely, GABPA bound at higher levels than ETV5 in well-differentiated thyroid cancer-derived cell lines, implicating potentially different roles of these specific ETS factors in well-differentiated and poorly differentiated cancers." (PMID 32849278, 2020). "Taken together, these data caution against GABPA being a universal regulator of the mutant TERT promoter in thyroid cancer cells and suggest that targeting GABPA over a sustained period is unlikely to result in a consistent reduction in TERT expression in this tumor type." (PMID 35053525, 2022). "Meanwhile, some researchers considered that GABPA might act as a tumor suppressor and restrained invasion and metastasis in thyroid carcinoma." (PMID 35958019, 2022). "The activating GA Binding Protein Transcription Factor Subunit Alpha (GABPA), a member of the ETS family, binds at the TERT promoter mutation site as a heterotetramer with its counterpart, GABPB, in multiple cancer types, including thyroid cancer." (PMID 32849278, 2020). "By promoting DICER1 expression, GABPA inhibits the invasive phenotype of thyroid cancer cells." (PMID 31285550, 2019). "Indeed, the dualistic properties of GABPA in this context and whether it should be regarded as a tumor suppressor or oncogene in thyroid cancer will need to be addressed in future studies." (PMID 32163919, 2020). "Conversely, factors such as ETS1 and ETV5 showed high and consistent expression across thyroid cancer types, whereas most ETS proteins, including GABPA, were expressed at intermediate levels." (PMID 35053525, 2022). "As our clinical samples showed a positive correlation between GABPA mRNA expression and DICER1 mRNA expression in thyroid cancer tissues, we sought to explore the relationship between these in FTC cell lines." (PMID 32163919, 2020). "Our results show that GABPA stable silencing does not universally reduce TERT transcription in TERT-mutant thyroid cancer cells and that it also controls TERT wildtype promoter (e.g., in Cal62 cells)." (PMID 35053525, 2022).
melanoma (8 papers, 2016 to 2025). A malignant, usually aggressive tumor composed of atypical, neoplastic melanocytes. "siRNA-mediated knockdown of ELF1 but not GABPA in A375 melanoma cells led to a significant reduction of CDC20." (PMID 38030698, 2023). "From the ETS family of TFs, ISMARA predicted GABPA, ELF2 and ELF5 with very low significance, while MIPRIP identified ETS1 as a highly significant regulator of TERT in the melanoma samples with a TERT promoter mutation." (PMID 31888467, 2019).
hepatocellular carcinoma (7 papers, 2017 to 2025). A malignant tumor that arises from hepatocytes. "In addition, another study revealed that it served as a novel biomarker for the prognosis of hepatocellular carcinoma since GABPA was able to block the migration of cancer cells by regulating E-cadherin." (PMID 36042907, 2022). "However, the function and clinicopathological significance of GABPA in hepatocellular carcinoma (HCC) remain obscure." (PMID 28549418, 2017).
glioma (4 papers, 2019 to 2025). A benign or malignant brain and spinal cord tumor that arises from glial cells (astrocytes, oligodendrocytes, ependymal cells). "In this study, we investigated the mRNA expression and association between TERT and GABPA/B isoforms in tumor samples of different glioma grades." (PMID 34194624, 2021). "The study showed that persistent oncogenic stress activated the AMPK–CREB1 pathway and regulated the transcription levels of HIF1α and GABPA to support glioma bioenergetics." (PMID 36715873, 2023). "We are the first to present an upregulation of all GABP components in the different glioma grades and GABPA, -B1, -B1-L, -B1-S are gradually expressed during malignancy progression from lower to higher grade while the most expression is observed in the sec." (PMID 34194624, 2021). "The results indicate that GABPA, -B1, -B1-L and -B1-S have the trend to progress with the malignancy of the gliomas." (PMID 34194624, 2021). "We analyzed the expression of the major ETS-factors ETS1, GABPA, and GABPB with its splice variants, ETV1, ETV4 and ETV5 all of which were widely expressed across our glioma cell panel." (PMID 31391125, 2019). "Our data point towards cooperation of GABPA with ETS1, especially in a BRAFV600E-mutant glioma background." (PMID 31391125, 2019). "We therefore can propose that GABP might be a potential biomarker in glioma classification, but further investigations must be made in order to elucidate the actual relationship between TERT and GABPA/B isoforms in gliomas, aiming for targeted therapy in the future." (PMID 34194624, 2021). "Next, we tested the impact of BRAF-inhibition on the expression of the respective ETS-factors and found that only ETS1 expression, but not expression of GABPA or the different GABPB splice variants, were significantly and consistently downregulated throughout all BRAFV600E-mutated glioma." (PMID 31391125, 2019). "GABPA protein expression, however, was not affected by BRAF-inhibition in double-mutant glioma cells." (PMID 31391125, 2019).
Intellectual disability (3 papers, 2015 to 2026). "Chromosome 21 transcription factors BACH1, PKNOX1 and GABPA emerged as dosage-sensitive hubs regulating genes linked to intellectual disability." (PMID 41545595, 2026). "Human METTL23, a MT Family 16 member without a yet described target, is associated with intellectual disability and interacts with the transcription factor GABPA." (PMID 26544960, 2015).
liver cancer (3 papers, 2020 to 2024). An epithelial or non-epithelial malignant neoplasm that arises from the liver. "The ChIP-seq of GABPA-expressing leukemic K562 and liver cancer HepG2 cells identified a total of 6,810 gene promoters bound by GABPA, and five genes were overlapped based on the integrated analyses above, among which was TGFBR2." (PMID 35549739, 2022).
papillary thyroid carcinoma (3 papers, 2022 to 2024). "Previous study reported that GABPA could inhibit the metastasis of papillary thyroid carcinoma through regulating DICER1." (PMID 36042907, 2022).
Alzheimer disease (2 papers, 2022 to 2023). A progressive, neurodegenerative disease characterized by loss of function and death of nerve cells in several areas of the brain leading to loss of cognitive function such as memory and language. "Moreover, ATP5J and GABPA are genes (male-biased CpGs) which have previously been reported to be implicated in early onset of Alzheimer’s disease, a disease known to affect females more than males." (PMID 35568878, 2022).
autism (2 papers, 2016 to 2022). Persistent deficits in social interaction and communication and interaction as well as a markedly restricted repertoire of activity and interest as well as repetitive patterns of behavior. "GABPA was recently found to bind human-specific binding sites and regulate gene expression of at least four genes (ALDOA, HSPA8, TP73, and TMBIM6) that have been associated with cognitive diseases such as autism, AZ, PD and other brain disorders." (PMID 27014338, 2016).
chronic myelogenous leukemia (2 papers, 2017 to 2022). "GABPA is necessary for chronic myeloid leukemia (CML) development through its regulation of protein kinase D2 (PRKD2)." (PMID 36035173, 2022). "Furthermore, a previous study showed that GABPA plays an important role in human chronic myelogenous leukemia (CML) and affects imatinib sensitivity." (PMID 28549418, 2017).